RN7SL688P (RNA, 7SL, cytoplasmic 688, pseudogene)
Gene: Miscellaneous RNA gene on chromosome 11 (118,931,216 to 118,931,490, forward strand). Ensembl gene ENSG00000239726.
Homologues: Orthologues: chimpanzee Metazoa_SRP (99% identical), pig Metazoa_SRP (65% identical), dog Metazoa_SRP (62% identical). Paralogues in human: RN7SL1 (74% identical), RN7SL2 (74% identical), RN7SL3 (74% identical), RN7SL18P (73% identical), RN7SL559P (73% identical), RN7SL218P (72% identical), RN7SL479P (72% identical), RN7SL822P (72% identical), RN7SL543P (72% identical), RN7SL220P (72% identical), RN7SL444P (72% identical), RN7SL672P (72% identical), and 700 more.